PRSS1 (serine protease 1)
Diseases named in the same sentence as PRSS1 in open-access papers (continued):
Sharing a sentence is not in itself a finding about the gene and the disease.
irritable bowel syndrome (1 paper, 2023). Irritable bowel syndrome (IBS) is a chronic functional condition of the lower gastrointestinal (GI) tract characterized by abdominal pain or discomfort and disordered bowel habit (diarrhea, constipation, or fluctuation between the two). "Using a systems pharmacology approach and molecular docking, the researchers investigated potential pathways for BXD treatment in the fight against irritable bowel syndrome (IBS) and predicted promising drug targets, such as PTGS2, NOS2, and PRSS1." (PMID 37836654, 2023).
lung adenocarcinoma (1 paper, 2024). A carcinoma that arises from the lung and is characterized by the presence of malignant glandular epithelial cells. "We observed that PRSS1 and CTCF mutations in lung adenocarcinomas and skin melanomas show similar resistance-conferring effects to KRAS and NRAS mutations when treated with EGFR and BRAF inhibitors." (PMID 39160568, 2024).
lung carcinoma (1 paper, 2023). "Moreover, we demonstrated that SS induced the high expression of PRSS3, but not PRSS1 or PRSS2, in circulating lung cancer cells to facilitate metastasis, suggesting a crucial role of PRSS3 in metastasis‐initiating CTCs." (PMID 37395651, 2023).
Meconium ileus (1 paper, 2019). Obstruction of the intestine due to abnormally thick meconium. "These assays and consideration that the encoded digestive enzyme function originates from the pancreas argue that variants associated with meconium ileus at the PRSS1 locus impact gene expression in this organ." (PMID 30807572, 2019).
multiple endocrine neoplasia syndrome type 1 (1 paper, 2022). "Only 10% of PDACs are linked to genetic mutations such as BRCA2, STK11/LKB1, CFTR, and PRSS1 or to familial syndromes such as Von Hippen-Lindau disease (VHL), multiple endocrine neoplasia syndrome type 1 (MEN-1), and neurofibromatosis type 1 (NF-1)." (PMID 36611999, 2022).
salivary gland cancer (1 paper, 2020). A primary or metastatic malignant neoplasm that affects the major or minor salivary glands. "Because both the pancreas and salivary glands are exocrine glands with a very similar histology, the PRSS1 mutation and resulting abnormal trypsinogen function may also be involved in the pathogenesis of salivary gland cancer." (PMID 31822803, 2020).
salivary gland tumors (1 paper, 2020). "The identification of a recurrent A16V mutation in the PRSS1 gene in secretory carcinoma is of clinical interest and warrants further in-depth studies as well in other subtypes of salivary gland tumors." (PMID 31822803, 2020).
Stroke (1 paper, 2022). Sudden impairment of blood flow to a part of the brain due to occlusion or rupture of an artery to the brain. "We hereby explored the association between blood-based HTRA serine protease 1 (HTRA1) methylation and the risk of stroke." (PMID 36581876, 2022).
T-cell acute lymphoblastic leukemia (1 paper, 2025). Acute lymphoblastic leukemia of T-cell origin. "For example, in Philadelphia chromosome-negative adult T-cell acute lymphoblastic leukemia, biallelic deletion of PRSS1 and PRSS2 has been observed in patients with clonal rearrangements within the TCRβ locus." (PMID 41141930, 2025).
cancer (18 papers, 2008 to 2025). A tumor composed of atypical neoplastic, often pleomorphic cells that invade other tissues. "Mutations and abnormal regulation of PRSS1 play important roles in the occurrence and development of malignant tumors." (PMID 33585454, 2020). "Second, the pathogenicity of several cancer-associated genetic variants, including PRSS1 c.161A > G, SLC22A18 c.257G > A, and RAD54B c.1778A > G, was misclassified." (PMID 30850667, 2019). "However, in our series, 1 case of SC with an intact ETV6 gene had the PRSS1 mutation, suggesting that other mechanisms may be involved in the PRSS1 mutation of zymogen granule-poor cancers." (PMID 31822803, 2020). "Another potential biomarker in cancer that has attracted much interest lately is serine protease 1 (PRSS1, PRoteaSe Serine 1), which codes for human cationic trypsinogen." (PMID 40382561, 2025). "All patients carried at least three mutated cancer genes, except for case 11 with only a FAM135B and case 15 with MUC16 and PRSS1 gene mutations." (PMID 38807144, 2024). "Cancer tissues/cells of platinum-resistant/sensitive patients were used to verify PRSS1 at the mRNA and protein expression levels." (PMID 33585454, 2020). "PRSS1 was silenced by siRNA, and the cisplatin-resistant cancer cells were tested for mRNA by RT-qPCR assay 24 h after transfection." (PMID 33585454, 2020). "PRSS1 mRNA expression level was examined by RT-qPCR, and the results confirmed its high expression in cancer tissues of cisplatin-resistant patients and low expression in cisplatin-sensitive patients, with a p-value of 0.035." (PMID 33585454, 2020). "The data showed that the protein expression of PRSS1 in A2780 and Skov3 cancer cells was higher than that in the normal control group, and the P-value was < 0.001." (PMID 33585454, 2020). "Given that PRSS1 exhibited high expression in cisplatin-resistant cell lines, A2780 and Skov3 cancer cell lines were constructed to overexpress PRSS1 by transfecting them with a plasmid to further explore the platinum-resistant properties of PRSS1." (PMID 33585454, 2020). "In our study, we manifested that PRSS1 was overexpressed in platinum-resistant cancer tissues/cells and lowly expressed in platinum-sensitive ones." (PMID 33585454, 2020). "Given the over-expression of PRSS1 in the constructed cancer cell lines, we examined the expression alterations in Bcl-2 and Bax at the mRNA and protein levels." (PMID 33585454, 2020). "Western blot analysis was used to detect protein expression, revealing that PRSS1 expression in cancer tissues from cisplatin-resistant patients was significantly higher than that in cisplatin-sensitive patients, with a P-value of 0.012." (PMID 33585454, 2020). "PRSS1 has also been reported to modulate several PARs, which are key players in cancer." (PMID 40382561, 2025). "Thus, both ADAM6 and PRSS1 can modulate several signaling cascades interrelated with leukemogenesis and cancer progression." (PMID 40382561, 2025). "Serine Protease-1 (PRSS1) is another emerging molecular mediator in cancer development." (PMID 40382561, 2025). "Higher ICI-4W expression of extracellular matrix (ECM) genes, including trypsinogens (PRSS1 and PRSS2) and matrix metalloproteases, and genes encoding cancer antigens (CTAG2, SAGE1, MAGEA1/A4/A10, POTEE, and PRAME) was significantly associated with ICI resistance and tumor growth during ICI-4W." (PMID 37433281, 2023). "However, as observed in A2780 cells, the total number of apoptotic cancer cells decreased due to the increased expression of PRSS1." (PMID 33585454, 2020). "In terms of previous test results, PRSS1 was overexpressed in cisplatin-resistant cancer cells." (PMID 33585454, 2020).
cancer (continued). "Given that zymogen granules contain many digestive enzymes, such as trypsin, mutant PRSS1 may be involved in the tumorigenesis of this zymogen granule–poor cancer." (PMID 31822803, 2020). "Therefore, PRSS1 knockdown increased the sensitivity of cisplatin-resistant cancer cells." (PMID 33585454, 2020). "For example, spots enriched with TM4SF1, PRSS1/2, and SERPINA1 are also predicted to, respectively, have high proportions of Cancer clone A cells, Acinar cells, and Ductal centroacinar cells." (PMID 37550279, 2023). "PRSS1 mRNA was highly expressed in cisplatin-resistant cancer cells (A2780DDP and Skov3DDP) compared with sensitive cancer cells (A2780 and Skov3), and the P-values were all significant." (PMID 33585454, 2020). "In cisplatin-resistant cancer cells, the mRNA expression of PRSS1 knockdown group was considerably lower than that of the normal control group, and the P-value was < 0.001." (PMID 33585454, 2020).
tumor (18 papers, 2001 to 2025). "The inverse correlation observed with the protein encoded by Prss1 was consistent with the recent demonstration of the key role of its downregulation, together with other mitochondrial lipid metabolic enzymes, in tumor growth." (PMID 33207594, 2020). "PRSS1 mutation and overexpression plays an “inside job” role in pancreatic carcinogenesis and tumor development." (PMID 31521106, 2019). "After filtering out mutations in healthy individuals and sorting mutations relevant to tumor or immunology, 586 gene mutations were ultimately identified, including PRSS1." (PMID 31521106, 2019). "Therefore, abnormal PRSS1 mutations trigger the amplification of tumor gene fragments and increase the abnormal expression of tumor-related proteins, thereby improving the ability to repair DNA damage." (PMID 33585454, 2020). "However, it remains unclear whether PRSS1 mutations promote pancreatic carcinogenesis by increasing trypsin expression or directly activating tumor pathways." (PMID 31521106, 2019). "ADAM6 was found to be significantly upregulated while PRSS1 was found to be downregulated in TARGET AML tumor samples compared to normal samples." (PMID 40382561, 2025). "ADAM6 was found to be significantly upregulated in TARGET AML tumor samples compared to normal (FC = 1.144, p ≤ 0.001), while PRSS1 was found to be downregulated in TARGET AML tumor samples compared to normal samples (FC = −1.698, p ≤ 0.001)." (PMID 40382561, 2025). "PRSS1, a T cell receptor protein, is an important molecule for tumor signal transduction and activity regulation." (PMID 33867821, 2021). "Together, our data demonstrate that PRSS1 protein expression was significantly increased in GC and was positively correlated with differentiation, tumor size, and lymph node metastasis." (PMID 33867821, 2021). "According to statistical analysis, PRSS1 overexpression was positively correlated with the differentiation, tumor size and lymph node metastasis of GC." (PMID 33867821, 2021). "Among them, PRSS1 protein was significantly overexpressed, which was positively correlated with the differentiation, tumor size and lymph node metastasis of GC." (PMID 33867821, 2021). "PANC-1 cells with overexpression of PRSS1_R116C (R116C) or wildtype- PRSS1 (OE) were subcutaneously implanted in nude mice at the same cell number to generate a tumor-bearing mouse model with low differentiation adenocarcinoma." (PMID 31521106, 2019). "Also, in TARGET ALL samples, ADAM6 was found to be significantly upregulated in ALL tumor compared to normal (FC = 1.434, p ≤ 0.001), while PRSS1 was significantly downregulated in ALL tumor against normal samples (FC = −1.515, p ≤ 0.001)." (PMID 40382561, 2025). "Additionally, some DGC patients tested negative for CDH1/CTNNA1 gene but had pathogenic variants in related tumor susceptibility genes, such as BRCA2, ATM, SDHB, PRSS1, MSR1, STK11, and PALB2." (PMID 37393258, 2023). "Furthermore, both ADAM6 and PRSS1 are emerging novel mediators of extracellular matrix (ECM) and tumor micro-environment (TME) remodeling." (PMID 40382561, 2025). "In the expression analysis of normal vs. tumour tissues, only PRSS1 was not significantly differentially expressed in normal versus tumour tissues." (PMID 37388244, 2023). "Compared with PANC-1 cells overexpressing wild type PRSS1 (OE), PRSS1_R116C-bearing PANC-1 cells (R116C) had stronger capacity of invasion and migration, indicating that PRSS1_R116C could promote tumor invasion and metastasis via other pathways." (PMID 31521106, 2019). "Restriction enzyme digestion analyses indicated that PRSS3 is expressed by tumor-EC while PRSS1 and PRSS2 are not." (PMID 26318044, 2015).
PRSS1 also shares sentences with these, for which no sentence is quoted: hereditary cancer syndrome (3 papers); infection (3); Peutz-Jeghers syndrome (3); acute lymphoblastic leukaemia (2); alcohol abuse (2); genetic conditions (2); hypertriglyceridemia (2); Leukoencephalopathy (2); melanoma (2); pancreatic disease (2); pancreatic ductal adenocarcinoma (2); adenocarcinoma (1); age-related macular degeneration (1); alcoholic pancreatitis (1); alcoholism (1); Allergy (1); Ataxia (1); Atrophy (1); autoimmune disease (1); autosomal dominant disease (1); CADASIL (1); COVID-19 (1); enterokinase deficiency (1); Failure to thrive (1); Familial adenomatous polyposis (1); familial atypical multiple mole melanoma syndrome (1); gastric adenocarcinoma (1); glaucoma (1); heart failure (1); hematological malignancies (1).
A further 28 diseases each share a sentence with PRSS1 in 1 paper.